LINC01994 (long independently transcribed non-coding RNA 1994)
Synonyms: CASCADES; LINC01995
Gene: Long non-coding RNA gene on chromosome 3 (182,215,209 to 182,618,285, reverse strand). Ensembl gene ENSG00000241098.
Diseases named in the same sentence as LINC01994 in open-access papers:
LINC01994 is named in the same sentence as 8 diseases in open-access papers, as found by Europe PMC text mining. Sharing a sentence is not in itself a finding about the gene and the disease.
LINC01994 shares sentences with these, for which no sentence is quoted: cancer (2 papers); astrocytomas (1); breast carcinoma (1); chronic myelogenous leukemia (1); colorectal cancer (1); diffuse intrinsic pontine glioma (1); glioblastoma (1); glioma (1).